ETV7 (ETS variant transcription factor 7)
Diseases named in the same sentence as ETV7 in open-access papers (continued):
Sharing a sentence is not in itself a finding about the gene and the disease.
tumor (continued). "However, during constitutively activated PI3K/Akt signaling due to loss of Pten, ETV7 enhanced myeloid colony-formation compared with PtenΔ/Δ control cells, suggesting that ETV7 works as a positive regulator in absence of the Pten tumor suppressor." (PMID 30478527, 2019). "When ETV7 is inhibited, it triggers the activation of interferon-stimulated genes, reduces STAT1 activation, and accelerates tumor growth." (PMID 41584509, 2025). "Our results confirmed that ETV7 and/or BATF2 knockdown elevates the PAI-1/ERK pathway, increasing BC cell tumor-promoting behaviors." (PMID 38282047, 2024). "We further investigated the TCGA database obtained from UALCAN software, which indicates the upregulation of AKT, mTOR, ETV7, and TAZ in tumor patients." (PMID 38791386, 2024). "Overexpression of snail downregulated cadherin expression through Snail-ETV7-SERPINE1 pathway, promoting EMT and enhancing tumor cell invasion and metastasis." (PMID 36261786, 2022). "Eight co-expressed genes (PSMB8, PSMB9, PSMB10, PSME2, TAP1, IRF1, FBOX6, ETV7) were identified as CD8+ T cell-related genes that promoted infiltration of CD8+ T cells, and were enriched in the MHC class I tumor antigen presentation process." (PMID 33330025, 2020). "Our results suggest that the tumour suppressive role of NOTCH1 in OSCC is mediated, at least in part, by inhibition of SERPINE1 via ETV7." (PMID 31827722, 2019). "Consistent with previous studies and our in vitro findings, there were inverse correlations between ETV7 and SERPINE1 expression and survival in OSCC primary tumours." (PMID 31827722, 2019). "We next compared the expression levels of ETV7 and SERPINE1 in SJG cell lines and the tumours from which they were derived." (PMID 31827722, 2019). "Overall, we proved that the transcription factor ETV7 was a novel prognostic factor, which may improve the individualized outcome prediction in BLCA by regulating the tumor immune microenvironment." (PMID 34926692, 2021). "Following the discovery of mRNA and protein overexpression in BLCA patients, we next analyzed the relationship between the mRNA expression of ETV7 with clinicopathological parameters of BLCA patients by UALCAN, including a patient's gender, smoking habit, tumor type, tumor stage, and N stage." (PMID 34926692, 2021). "In addition, ETV7 expression was inversely correlated with SERPINE1, since the SJG6 parental tumour and cell line had higher levels of SERPINE1 than the SJG26 parental tumour and cell line." (PMID 31827722, 2019). "Like wild-type (WT) controls ETV7 heterozygous (ETV7Tg+/WT or ETV7Tg) mice develop normally, are not tumor-prone and have a normal lifespan." (PMID 30478527, 2019). "All mice developed a variety of tumors and ETV7 did not affect the tumor spectrum of Arf−/− and Ink4aArf−/− mice." (PMID 30478527, 2019). "ETV7 was not exclusively expressed in T cells but could be detected in several types of cells, including tumor cells (green circle), T cells, and macrophages." (PMID 33424867, 2020). "With the ETV7 expression in hematopoietic cells considered, the strong correlation between ETV7 and the infiltration of CD8+ T cells may be attributed to ETV7 expression in T cells rather than tumor cells." (PMID 33424867, 2020). "Accumulating experimental evidence indicates that ETV7 also plays a significant role in the mTOR signaling pathway by assembling the mTOR3 complex, which can stimulate cell proliferation and is not sensitive to rapamycin, a common anti-tumor agent, unlike mTOR1/2." (PMID 33424926, 2020).
cancer (18 papers, 2014 to 2024). A tumor composed of atypical neoplastic, often pleomorphic cells that invade other tissues. "Among them, ETV7 was identified as the key DE-TFs due to its association with the autophagy activation pathway and various immune cells in cancer." (PMID 34926692, 2021). "The ETV7Tg mouse is therefore a more faithful cancer animal model to investigate ETV7-associated human tumors." (PMID 30478527, 2019). "We believe that our ETV7Tg mouse not only enables us to more faithfully model human ETV7-associated tumorigenesis in vivo but also provides a preclinical model with which to test efficacy of future drugs directed against ETV7-positive human cancers." (PMID 30478527, 2019). "Interestingly, a recent report shows that K562 cells express a distinct mTOR-containing complex, mTORC3 (mTOR associated with ETV7) that lacks other mTORC1/2 containing proteins, and is associated with rapamycin-resistance when upregulated in human cancer cells." (PMID 31729420, 2019). "Moreover, our ETV7Tg mouse model, which faithfully recapitulates human tumors, might greatly facilitate the identification of therapeutic targets for ETV7-associated human cancer." (PMID 30478527, 2019). "Our newly conjugated gold nanoparticles with a vitamin dosage act by downregulating the novel transcription factor ETV7 and two important cancer signaling pathways." (PMID 38791386, 2024). "In the nucleus, ETV7 mostly functions as a transcriptional repressor and is known to be upregulated in various types of cancer." (PMID 39337528, 2024). "The correlation between ETV7 with clinicopathological parameters by UALCAN shown that the ETV7 was remarkably correlated with cancer stage." (PMID 34926692, 2021). "We have started crossing the ETV7Tg mice with various other cancer mouse models to determine if ETV7 also accelerates tumorigenesis in those models in vivo." (PMID 30478527, 2019). "There is now a need to gain a more complete understanding for the effects of etv7 overexpression and the potential role of this gene in a zebrafish cancer model system." (PMID 24357328, 2014). "We hypothesize that the ETV7-dependent reduced activation of NF-κB could help cancer cells evade the host immune response, as proper stimulation is essential for both innate and adaptive immune responses." (PMID 37041130, 2023). "Moreover, the expression of ETV7 increased according to cancer aggressiveness, and it was significantly higher in basal-like samples compared to the other molecular subtypes." (PMID 34315857, 2021). "Notably, ETV7 is upregulated in a variety of different human cancers and, when introduced into murine bone marrow, can cooperate with other oncogenes to cause hematopoietic malignancy." (PMID 24357328, 2014). "Uncovering these mechanisms could lead to the development of new models in which to characterize the role of etv7 during development and disease, and to the discovery of new cancer therapies." (PMID 24357328, 2014). "Cells expressing ETV7 assemble mTORC3, whose kinase activity induces increased proliferation and renders cells resistant to rapamycin, indicating that inhibiting mTORC3 may be of therapeutic value for the treatment of cancer." (PMID 39337528, 2024). "We sought to identify whether ETV7-mediated cancer progression is based on the expression of IFIT3." (PMID 38200280, 2024). "Furthermore, the appearance of mTORC3 seems to be triggered by ETV7, especially in cancer cells with high ETV7 expression, and might contribute to rapamycin insensitivity in many cancers." (PMID 32799865, 2020). "All of these enrichment analyses suggest broad ETV7 involvement in immune-related processes and pathways, including the following: T cell activation; Th1, Th2, and Th17 cell differentiation; PD-L1 expression and PD-1 checkpoint pathway in cancer; and antigen processing and presentation." (PMID 33424867, 2020).
cancer (continued). "For now, mTORC3 contains ETV7 and other undefined components, while mTORC4 includes mEAK7 and DNA-PKcs, which are hypothesized to play roles in tumorigenesis and anti-cancer drug resistance by controlling T cell’s response to DNA damage and cancer cell physiology." (PMID 39273395, 2024). "ETV7 is a TF belonging to the ETS family, which is responsible for the development of different tissues as well as the progression of several cancers, such as HCC." (PMID 33424926, 2020). "Transcription factor (TF) motifs, including CEBPB (+), FOSB (+), SAP30 (+) and ATF4 (+), were significantly upregulated in CNV high cancer cells, while IRF3 (+), ETV7 (+), STAT1 (+) and IRF7 (+) were downregulated, indicating promising new regulatory networks driven by TFs in OS cells." (PMID 36596773, 2023). "Moreover, we unveil a negative crosstalk between ETV7 and STAT3 in the regulation of the TNFRSF1A gene, and this crosstalk highlights the importance of ETV7 in cancer immunity and inflammation." (PMID 37041130, 2023).
infection (2 papers, 2021 to 2024). The state of being infected such as from the introduction of a foreign agent such as serum, vaccine, antigenic substance or organism. "In LB patients included in this dataset, amongst several up- and downregulated genes, the ETV7 and KTCD20 genes were upregulated in the acute phase of infection, before start of antibiotic treatment." (PMID 38515037, 2024).
ETV7 also shares sentences with these, for which no sentence is quoted: asthma (1 paper); B-cell lymphoma (1); bladder tumor (1); breast invasive carcinoma (1); COVID-19 (1); gout (1); head and neck squamous cell carcinoma (1); invasive ductal carcinoma of the breast (1); lung adenocarcinoma (1); medulloblastoma (1); oral squamous cell carcinoma (1); Primary biliary cirrhosis (1); psoriasis (1); sarcoidosis (1); skin cutaneous melanoma (1); thyroid carcinoma (1); triple-negative breast carcinoma (1); tuberculosis (1); ZIKV infection (1).